BAP1 (BRCA1 associated deubiquitinase 1)
Diseases named in the same sentence as BAP1 in open-access papers (continued):
Sharing a sentence is not in itself a finding about the gene and the disease.
pancreatic ductal adenocarcinoma (5 papers, 2016 to 2025). An infiltrating adenocarcinoma that arises from the epithelial cells of the pancreas. "The deubiquitinating enzyme BRCA1 Associated Protein-1 (BAP1) has been reported to be shallowly deleted in a subset of pancreatic ductal adenocarcinomas (PDAC) and is believed to play a significant role in the development of chronic pancreatitis-driven PDAC." (PMID 40083694, 2025). "Considering the higher incidence of heterozygous loss of BAP1 in individuals diagnosed with pancreatic ductal adenocarcinoma, we established a shBAP1 cell line to more accurately replicate the pathological state observed in PDAC patients." (PMID 40083694, 2025). "Loss of BAP1 expression was found in only 1 of 306 (0.33%) pancreatic ductal adenocarcinomas." (PMID 26982343, 2016). "We find that heterozygous loss of histone H2A lysine 119 deubiquitinase BAP1 (BRCA1 Associated Protein-1) associates with a history of chronic pancreatitis and occurs in 25% of pancreatic ductal adenocarcinomas and 40% of acinar cell carcinomas." (PMID 32541668, 2020). "Furthermore, the deficiency of BAP1 triggers the ubiquitination and subsequent degradation of LATS2, ultimately culminating in the deregulation of the Hippo signaling pathway and the induction of pancreatic ductal adenocarcinoma in murine models." (PMID 40083694, 2025).
pheochromocytoma (5 papers, 2017 to 2025). "The other rare autosomal dominant disorders associated with chRCC include BAP1 tumor predisposition syndrome (BAP1 gene), hereditary paraganglioma/pheochromocytoma (PGL/PCC) syndrome (SDH A/B/C/D genes), Cowden syndrome (PTEN mutations), and tuberous sclerosis (TSC1/2 mutations)." (PMID 39585048, 2024). "Mutations in some genes have been found only in single patients or families (e.g., MEN1, EGLN1, EGLN2, MDH2, IDH1, BAP1, BRAF); therefore, their role in the formation of paragangliomas/pheochromocytomas cannot be reliably confirmed." (PMID 28187001, 2017).
tumor syndrome (5 papers, 2018 to 2024). "The hereditary BAP1 tumor syndrome is a relatively uncommon condition characterized by mutations in the BRCA-associated protein-1 gene (BAP1) located on chromosome 3p21.1." (PMID 39201746, 2024). "BAP1-inactivated melanocytic tumours (BIM) have since been considered to be a feature of BAP1-associated tumour syndrome, identified in up to 72% of cases." (PMID 37607989, 2023). "Additionally, a germline BAP1 mutation was noted, indicative of a predisposition to BAP1 tumor syndrome." (PMID 39156348, 2024).
dysplastic nevi (4 papers, 2019 to 2023). "Risk factors for UM include a fair skin color, red or blond hair, light eye color, ocular melanocytosis and dysplastic nevi, cutaneous, iris or choroidal nevus, and familial syndromes, i.e., germline BRCA1-associated protein-1 (BAP1) mutations." (PMID 35349481, 2022). "Risk factors include fair skin colour, red or blond hair, light eye colour, ocular melanocytosis and dysplastic nevi, and familial syndromes, i.e., germline BRCA1-associated protein-1 (BAP1) mutation)." (PMID 31200439, 2019).
gall bladder cancer (4 papers, 2018 to 2023). "Comparing ICC with gall bladder cancer, ICC has significantly higher IDH1 (14.5%), BAP1 (9.5%), and PBRM1 (7.5%) mutation rates." (PMID 38203635, 2023).
gastric cancer (4 papers, 2013 to 2025). A primary or metastatic malignant neoplasm involving the stomach. "This study did not conduct experiments to support the function of highly frequent, methylated SFR genes, including BAP1, in gastric cancer." (PMID 39000483, 2024). "In particular, BAP1 is a well-known TSG, and its role in gastric cancer has also been identified." (PMID 39000483, 2024).
Küry-Isidor syndrome (4 papers, 2024 to 2026). "This in vitro assay provides supporting evidence to the ACMG/AMP guidelines used to guide clinical interpretation of BAP1 variants in the context of dominant cancer predisposition and the neurodevelopmental Kury-Isidor syndrome." (PMID 37956408, 2024).
Li-Fraumeni syndrome (4 papers, 2018 to 2022). "Similarly to patients with the Li-Fraumeni syndrome, BAP1 mutations are highly penetrant, and so far most carriers of BAP1 mutations have developed one or more malignancies during their lifetime." (PMID 30001711, 2018).
metastatic carcinoma (4 papers, 2020 to 2024). A carcinoma which has spread from the original site of growth to another anatomic site. "BAP1 loss is also very useful in the differentiation of PM from metastatic cancers from various sites to the pleura that generally retain the protein in the nuclei." (PMID 38673021, 2024). "BAP1 was expressed at higherlevels in metastatic cancer samples compared with that in primary tumor samples(p < 0.01, Student’s t-test)." (PMID 32422649, 2020). "In a practical algorithm, BAP1 and claudin-4 seems to represent the best panel for differentiating MPM with epithelioid features and metastatic carcinoma either on cytology or biopsy." (PMID 34070888, 2021).
mucosal melanoma (4 papers, 2018 to 2025). A melanoma that arises from a mucosal site. "BAP1 loss of function mutations often lead to loss of nuclear BAP1 (nBAP1) expression in humans; this is associated with a poorer prognosis in uveal and mucosal melanoma." (PMID 30060843, 2018). "This is the first reported case of mucosal melanoma in association with BAP1-TPDS." (PMID 31382694, 2019). "Conjunctival and other mucosal melanomas have not been included in the BAP1-TPDS spectrum and larger cohorts of BAP1-TPDS individuals need to be studied to determine a possible association." (PMID 31382694, 2019).
myeloid leukemia (4 papers, 2018 to 2026). A clonal proliferation of myeloid cells and their precursors in the bone marrow, peripheral blood, and spleen. "Although these studies have clearly shown a tumor suppressor role for BAP1, several lines of evidence also raise the possibility that BAP1 activity drives the growth of myeloid leukemia cells with ASXL1 mutations." (PMID 30013160, 2018). "Thus, BAP1 has a growth-promoting effect in a wide range of myeloid leukemia cells, including AMLs with ASXL1 mutations or MLL-fusions." (PMID 30013160, 2018). "BAP1 knockdown across multiple myeloid leukemia cell lines selectively decreased HLA-E and IFN-γ-R1 expression in ASXL1-mutant backgrounds." (PMID 42295372, 2026). "BAP1 depletion resulted in substantial growth inhibition in all of these myeloid leukemia cell lines." (PMID 30013160, 2018). "Importantly, Bap1 depletion using CRISPR/Cas9 substantially inhibits the leukaemogenicity of myeloid leukemia cells expressing mutant ASXL1." (PMID 30013160, 2018). "Finally, we assessed the role of BAP1 in several human myeloid leukemia cell lines." (PMID 30013160, 2018). "Importantly, BAP1 depletion inhibits posterior HOXA gene expression and leukaemogenicity of ASXL1-MT-expressing myeloid leukemia cells." (PMID 30013160, 2018).
Obesity (4 papers, 2013 to 2025). Accumulation of substantial excess body fat. "TMBIM4 is located within ±1 Mb of the SNP rs1531343 conferring susceptibility to T2DM, while NCKAP5L, TOMM5, and BAP1 are mapped within ±1 Mb of SNPs conferring susceptibility to obesity." (PMID 24455749, 2013). "Moreover, obesity can regulate the mutation of oncogenes, such as Kirsten rat sarcoma virus (KRAS), epidermal growth factor receptor (EGFR), SET domain-containing 2 protein (SETD2), and BRCA1-associated protein 1 (BAP1), which also increases the risk of cancer development." (PMID 40863244, 2025). "Using the same method, seven highly ranked genes (BAP1, GRB14, HSP90AB1, ITGA5, NCKAP5L, SP1, and TOMM5) within ±1 Mb of obesity SNPs were identified." (PMID 24455749, 2013). "The rest of the candidates, C2orf15, DENND1B, MRPL30, POC1B, RP4-655J12.3, TMBIM4, BMP2 K, CSRNP2, NCKAP5L, TOMM5, and BAP1, may be novel genes related to T2DM or obesity." (PMID 24455749, 2013).
sarcomatoid mesothelioma (4 papers, 2020 to 2024). A diffuse malignant mesothelioma arising from the pleura and less often the peritoneum. "Sarcomatoid mesothelioma (SM) is diagnosed less often than epithelioid disease, and can be challenging to diagnose as BAP1 loss is seen less frequently than in epithelioid disease." (PMID 39409190, 2024). "In contrast, the SMs were all negative for Claudin-4 and showed a BAP1 loss in 56.1% (23/41) of the cases, varying from 53.6% (15/28) of sarcomatoid mesotheliomas to 61.5% (8/13) of desmoplastic mesotheliomas." (PMID 36673059, 2023). "BAP-1 negativity and GATA binding protein 3 (GATA3) positivity have been recently described to be very helpful in ruling out PSC and supporting the diagnosis of sarcomatoid mesothelioma." (PMID 32149365, 2020).
breast tumor (3 papers, 2015 to 2022). "Immunohistochemical staining performed on patient’s breast tumor tissue showed loss of BAP1 nuclear expression in tumor cells." (PMID 35381901, 2022). "Interestingly, authors presented evidence for loss of heterozygosity at the BAP1 locus in the proband’s breast tumor." (PMID 35381901, 2022). "Nevertheless, our results suggest that BAP1 promotes breast tumour growth and metastasis partially through stabilizing KLF5." (PMID 26419610, 2015). "We analysed the BAP1 mRNA expression levels in breast tumours based on the TCGA database." (PMID 26419610, 2015). "Therefore, it is important to develop a good antibody examining the BAP1 protein expression in breast tumours by immunohistochemical staining in the future." (PMID 26419610, 2015). "Unfortunately, two commercially available anti-BAP1 antibodies did not work for immunohistochemical staining in breast tumours." (PMID 26419610, 2015). "Finally, BAP1 promotes breast tumour growth and metastasis partially through KLF5, because KLF5 overexpression partially rescued the BAP1 knockdown-induced tumour growth and metastasis inhibition." (PMID 26419610, 2015).
colorectal adenocarcinoma (3 papers, 2017 to 2023). The most common type of colorectal carcinoma. "However, TCGA PanCancer Atlas analysis showed that somatic mutations and deep deletion of the BAP1 gene are rare in colorectal adenocarcinoma (10 of 594 cases, 1.68%)." (PMID 36754982, 2023).
esophageal cancer (3 papers, 2017 to 2021). A primary or metastatic malignant neoplasm involving the esophagus. "BAP1 mutations are early and rare events in esophageal carcinoma, but the involvement of BAP1 in progression of esophageal carcinoma is unclear." (PMID 33529461, 2021). "BAP1 mutations have been reported as early and rare events in esophageal cancer." (PMID 33529461, 2021). "However, whether BAP1 regulates KLF5 expression in esophageal cancer is unclear." (PMID 33529461, 2021). "Our data suggest that BAP1 promotes cell proliferation and migration, and enhances the expression of KLF5 and its downstream genes, including CyclinD1 and FGF‐BP1, in the esophageal carcinoma cell line ECA109." (PMID 33529461, 2021). "Here, we report that cell proliferation and migration were significantly enhanced in esophageal carcinoma ECA109 cells overexpressing BAP1, while they were diminished upon BAP1 knockdown." (PMID 33529461, 2021).
invasive breast carcinoma (3 papers, 2019 to 2020). A carcinoma that infiltrates the breast parenchyma. "Since the number of cases in TCGA-BRCA was much higher than TCGA-UVM, we obtained highly correlated genes with BAP1 in invasive breast carcinomas." (PMID 30716094, 2019). "In patients with breast invasive carcinomas, BAP1 is highly positively correlated with NSG00000132153.13 (DHX30), ENSG00000259956.1 (RBM15B), and ENSG00000172046.17 (USP19), in all four categories." (PMID 30716094, 2019). "We found that BAP1 is highly positively correlated with RBM15B and USP19 expression in invasive breast carcinoma, UM, and colon adenocarcinoma." (PMID 30716094, 2019).
myeloproliferative disease (3 papers, 2015 to 2024). "In mouse models, conditional deletion of BAP1 in hematopoietic cells led to a fully penetrant myeloproliferative disease with universal splenomegaly." (PMID 38824259, 2024). "In contrast, BAP1 function is required to avoid the onset of myeloproliferative disorder since BAP1 KO mice showed hematopoietic defects as myeloid progenitor expansion." (PMID 36318367, 2022). "Pre-clinical data suggests a role for BAP1 in splenic growth and myeloproliferative disease." (PMID 38824259, 2024).
neurofibromatosis type 1 (3 papers, 2019 to 2025). A clinically heterogeneous, neurocutaneous genetic disorder characterized by cafe-au-lait spots, iris Lisch nodules, axillary and inguinal freckling, and multiple neurofibromas. "In rare instances, UM occurs in the presence of predisposing factors (e.g., oculo(dermal) melanocytosis, dysplastic nevus syndrome, neurofibromatosis type 1 and germline mutations in the BRCA1-associated protein 1 (BAP1) gene." (PMID 37760619, 2023).
Ocular melanocytosis (3 papers, 2019 to 2022). A congenital lesion of the sclera characterized by unilateral patchy but extensive slate-gray or bluish discoloration of the sclera . "The median age at diagnosis is about 62 years, and risk factors include fair skin, light eye color (green or blue), ocular melanocytosis, dysplastic nevus syndrome, germline BRCA1-associated protein 1 (BAP1) mutations, and welding as an occupation." (PMID 34944815, 2021).
Parkinson disease (3 papers, 2010 to 2022). A progressive degenerative disorder of the central nervous system characterized by loss of dopamine producing neurons in the substantia nigra and the presence of Lewy bodies in the substantia nigra and locus coeruleus. "In the current study, BAP1 was associated with selective regional vulnerability in Parkinson’s brain." (PMID 36506471, 2022).
prostate adenocarcinoma (3 papers, 2017 to 2021). "The mRNA levels of BAP1 were downregulated in the prostate adenocarcinoma (PRAD) specimens as compared with those in normal tissue specimens, which datasets were obtained from The Cancer Genome Atlas (TCGA) public PRAD and The Genotype‐Tissue Expression (GTEx) public normal prostate tissues." (PMID 33155366, 2021).
Splenomegaly (3 papers, 2021 to 2024). Abnormal increased size of the spleen. "Based on their findings, BAP1-cKO mice leads to the development of splenomegaly within 4 weeks of BAP1 depletion, and myeloid cells were significantly increased in lymph nodes and bone marrow in BAP1-cKO mice, resulting in myeloid transformation." (PMID 33483476, 2021).
bile duct cancer (2 papers, 2018 to 2025). "Meanwhile, the suppression of BAP1 by siRNA in bile duct cancer cell lines enhanced the proliferative capacity." (PMID 30395583, 2018).
bone metastasis (2 papers, 2017 to 2021). Transfer of a neoplasm from its primary site to bones. "The primary tumor for this patient was BAP1 positive, whereas the first bone metastasis was IHC negative, and the second bone metastasis) was IHC positive." (PMID 34885018, 2021). "The primary tumor for this patient was BAP1 IHC positive, the first bone metastasis (synchronous) was IHC negative and the second bone metastasis (diagnosed approximately 9 months later) was IHC positive." (PMID 28327121, 2017).
cardiomyopathy (2 papers, 2025). A disease of the heart muscle or myocardium proper. "The cardiomyopathy-associated targets were Dnmt1, Hdac1, Dot1l, Setd5, Nsd2, Usp3, Bap1, Prkca, Prkcb, Crebbp and Clock: 11 out of 81 (13.6% of total targets)." (PMID 40076868, 2025). "Additionally, miR-31-5p alleviates sepsis-induced cardiomyopathy by inhibiting the deubiquitination of SLC7A11 via targeting BAP1, thereby also counteracting ferroptosis." (PMID 40041174, 2025).
chronic pancreatitis (2 papers, 2020 to 2025). A chronic inflammatory process causing damage and fibrosis of the pancreatic parenchyma. "The loss of BAP1 leads to genomic instability, which contribute to chronic pancreatitis and predisposes to cancer development." (PMID 40083694, 2025). "We found that loss of BAP1 leads to the development of chronic pancreatitis in mice and is associated with poor prognosis in PDA patients." (PMID 32541668, 2020). "Previous study also proved BAP1 is pertaining to NF-κB pathway, and link the chronic pancreatitis to cancer." (PMID 40083694, 2025).
colon adenocarcinoma (2 papers, 2019 to 2023). "We also obtained the genes that were highly correlated with BAP1 in samples obtained from primary tumor of patients with colon adenocarcinoma." (PMID 30716094, 2019). "In addition, we analyzed BAP1 expression in colon adenocarcinoma and normal colon tissues using a tissue microarray." (PMID 36754982, 2023). "Importantly, USP19 and RBM15B were also among 10 genes with a high positive correlation with BAP1 expression in colon adenocarcinoma." (PMID 30716094, 2019).
cutaneous melanocytic neoplasm (2 papers, 2021 to 2023). "BAP1 is a tumor suppressor gene and individuals with cutaneous melanocytic neoplasm with a germline BAP1 mutation, often have BRAF mutations, with these lesions reported to have a benign clinical course." (PMID 34071371, 2021).
diabetes (2 papers, 2023 to 2024). "Due to limitations of a retrospective study, only partial information was available for asbestos exposure, Eastern Cooperative Oncology Group (ECOG) performance status prior to chemotherapy, smoking status, diabetes, and BAP-1 expression." (PMID 37026006, 2023).
endometrial carcinoma (2 papers, 2020 to 2022). A malignant tumor arising from the epithelium that lines the cavity of the uterine body. "Nevertheless, BAP1 was found to be rarely investigated in endometrial cancer." (PMID 35847989, 2022). "One case report revealed that the negative expression of BRCA1-associated protein 1 (BAP1) was observed in the peritoneal masses after endometrial cancer surgery." (PMID 35847989, 2022).
Ewing sarcoma (2 papers, 2016 to 2023). A small round cell tumor that lacks morphologic, immunohistochemical, and electron microscopic evidence of neuroectodermal differentiation. "The second was a father whose 18-year-old daughter with Ewings sarcoma was found to carry a P/LP BAP1 variant." (PMID 38138883, 2023).
fibrolamellar carcinoma (2 papers, 2023 to 2024). "In the first dataset (GSE215785), common fibrolamellar carcinoma mutant backgrounds were generated, including BAP1 single-knockout and BAP1/PRKAR2A double-knockout organoids." (PMID 39554490, 2024).
iris tumor (2 papers, 2020 to 2022). "Patients with wildtype BAP1 or one with an iris tumor exhibiting UV damage had a response or longer survival." (PMID 34753889, 2022). "As in UM, mutations in BAP1, EIF1AX and SF3B1 are frequently seen in iris tumours." (PMID 32998469, 2020).
melanocytic nevus (2 papers, 2021 to 2026). A neoplasm composed of melanocytes that usually appears as a dark spot on the skin. "The results of the lower back lesion shave biopsy revealed a BAP1-deficient intradermal melanocytic nevus." (PMID 41551629, 2026).